BCL2 (BCL2 apoptosis regulator)
Diseases named in the same sentence as BCL2 in open-access papers (continued):
Sharing a sentence is not in itself a finding about the gene and the disease.
tuberculosis (8 papers, 2006 to 2026). A chronic, recurrent infection caused by the bacterium Mycobacterium tuberculosis. "In summary, our data describes a novel regulatory complex between BAT3 and BCL-2, thereby providing new insights into the basic physiology of macrophage cell death in tuberculosis." (PMID 22808273, 2012). "This correlates with previous studies where reduced Bax and increased Bcl-2 mRNA expression has been shown to be responsible for slowly progressive murine tuberculosis." (PMID 16978419, 2006). "Here, we demonstrate that navitoclax, an orally bioavailable, small-molecule Bcl-2 inhibitor, significantly improves pulmonary tuberculosis (TB) treatments as a host-directed therapy." (PMID 39281866, 2024).
adenoid cystic carcinoma (7 papers, 2009 to 2025). A malignant tumor arising from the epithelial cells. "The neoplastic population also showed strong expression of Bcl-2 and CD117 (c-KIT), two markers commonly associated with adenoid cystic carcinoma (AdCC), thereby supporting the diagnosis." (PMID 41133536, 2025). "Other major proliferation or anti-apoptotic markers, such as Ki-67, bcl-2, and cyclin D1, were frequently expressed in adenoid cystic carcinoma, but they had less of an impact on the discrimination of histological grade of adenoid cystic carcinoma." (PMID 19250538, 2009). "IHC Diagnostic Interpretation: The immunophenotypic profile—characterized by epithelial marker expression (AE1/AE3, CK7), positivity for CD117 and Bcl-2, and the presence of myoepithelial cells identified by p63, p40, and calponin—was highly consistent with adenoid cystic carcinoma of the larynx." (PMID 41133536, 2025). "Likewise, bcl-2 immunohistochemical expression was also studied by investigators to distinguish adenoid cystic carcinoma from polymorphous adenocarcinoma, but the results were not statistically significant." (PMID 31653135, 2019).
adenomyosis (7 papers, 2015 to 2026). The growth of endometrial tissue inside the muscular wall of the uterine corpus. "Estradiol receptor (ER) expression in the adenomyosis foci is greater than in normal endometrium and it is associated with the expression of the apoptosis-suppressing gene product, Bcl-2, throughout the menstrual cycle." (PMID 26330846, 2015). "Research indicates that aberrant activation of β-catenin and the overexpression of Bcl-2 contribute to the pathogenesis of adenomyosis, suggesting their potential as therapeutic targets for this condition." (PMID 39595579, 2024). "In summary, GSK-3β serves as a key link between proteins such as PI3K/AKT and Bcl-2, making it a potential target for the treatment of adenomyosis." (PMID 39595579, 2024). "At the same time, compared with the adenomyosis group, the expression of Bcl2 was decreased, the expression of Bax was increased, and Bcl2/Bax was decreased, while the expression of PCNA was decreased in the verteporfin group." (PMID 36940085, 2023). "The co-expression of Bcl-2 and ER and the hyper-oestrogenic metabolic states may promote both the invagination process and overall ‘spreading’ of adenomyosis into the myometrium." (PMID 26330846, 2015). "Key downstream targets of GSK-3β, including vimentin, Bcl-2, snail, and α-SMA, are highly expressed in adenomyosis lesions." (PMID 39595579, 2024).
bladder tumors (7 papers, 2014 to 2024). "Because a decrease in BCL-2 expression results in the reduced proliferation of tumor cells, HB should be considered a suitable agent for reducing the expression of BCL-2 in bladder tumors." (PMID 38930984, 2024). "Under hypoxia, UCA1 inhibits apoptosis in bladder tumors cells and promotes their viability by modulating the BCL2-associated X, apoptosis regulator (BAX)/BCL2 apoptosis regulator (BCL2) ratio." (PMID 35659268, 2022). "The first objective of this study was to identifythe role of Bax gene expression in the clinical outcomeof low-grade bladder tumors expressing Bcl-2 mRNA." (PMID 24381861, 2014). "We have validated these markers together with BCL2 in a panel of 51 bladder tumors representing various tumor stages (22 low grade Ta tumors, 2 high grade Ta tumors, 8 T1 tumors, 17≥T2 tumors, and 2 Tis)." (PMID 24732047, 2014). "Seven out of the 15 urine samples were positive for this marker, consistent with previous reports showing BCL2 hypermethylation in a large percentage of bladder tumors." (PMID 24732047, 2014). "In addition, the present study demonstrates that in bladder tumors, apoptosis is inhibited by increased expression levels of the BCL2 gene." (PMID 25295115, 2014).
gastrointestinal stromal tumor (7 papers, 2007 to 2024). "The overexpression of ETV1 in gastrointestinal stromal tumors can increase the expression of anti-apoptotic proteins, Bcl-2, and decrease the expression of pro-apoptotic proteins, Bax, thereby inhibiting tumor cell apoptosis." (PMID 34736492, 2021). "The tumor cells are often positive for CD34, CD99, vimentin and BCL-2, and negative for CD117 (in gastrointestinal stromal tumors), smooth muscle actin (SMA) and desmin (in smooth muscle tumors) and S-100 protein (in nerve sheath tumors)." (PMID 25884588, 2015). "Bcl-2 and vimentin are typically immunoreactive in SFTs in addition to CD34 and STAT6, but SMA and desmin (a marker for myocytes), S-100 and synaptophysin (a marker for perineural tissue), or c-kit (a marker for gastrointestinal stromal tumors) are generally negative." (PMID 39435031, 2024).
hemangiopericytoma (7 papers, 2007 to 2020). An antiquated term that refers to benign or malignant mesenchymal neoplasms characterized by the presence of neoplastic spindle-shaped to round cells arranged around thin-walled branching vascular spaces. "Hemangiopericytoma is one of the lesions that bears a close resemblance with SFT of soft tissues (fascicular pattern, fibrosis, and vimentin, CD34, and bcl2 immunoreactivity)." (PMID 17577399, 2007). "The histopathologic examination and immunohistochemistry staining results (positive for CD34, CD31 and smooth muscle actin, but negative for CD99, S100, B-cell lymphoma 2 (bcl-2) and desmin) confirmed the diagnosis of hemangiopericytoma." (PMID 29785407, 2018).
hypopharyngeal carcinoma (7 papers, 2014 to 2025). Carcinoma, predominantly squamous cell, arising from the epithelial cells of the hypopharynx. "Based on these findings, many strategies to overcome chemotherapy resistance in hypopharyngeal carcinoma target the Bcl-2/Bax-associated intrinsic pathway." (PMID 41153768, 2025). "The downregulation of Bcl-2 by metformin treatment was linked with an increased apoptosis in present hypopharyngeal cancer cells." (PMID 33652909, 2021). "We demonstrate that the administration of BAY 11-7082, either before or after acidic bile, eliminates NF-κB activation, prevents overexpression of Bcl2, Rela, Stat3, Egfr, Tnf, Wnt5a, and deregulations of miR-192, miR-504, linked to bile reflux-related hypopharyngeal cancer." (PMID 32934775, 2020). "Among these, the Bcl-2/Bax-mediated mitochondrial intrinsic apoptotic pathway plays a critical role in chemotherapy resistance in hypopharyngeal carcinoma and serves as a downstream mechanism for resistance to multiple chemotherapeutic agents." (PMID 41153768, 2025). "It is widely thought that c-Jun might function similarly in hypopharyngeal carcinoma as in nasopharyngeal carcinoma, where it upregulates Bcl-2 to inhibit apoptosis and confer Chemoresistance." (PMID 41153768, 2025). "However, studies have revealed that hypopharyngeal carcinoma cells frequently exhibit Bcl-2 overexpression and Bax downregulation, resulting in impaired apoptotic signaling and significantly enhanced cisplatin resistance." (PMID 41153768, 2025). "We also show that all three STAT3 inhibitors, with STA‐21 having the most profound effect, can effectively suppress the continuous production of cancer‐related molecules, IL6, TNF, RELA(p65), EGFR, BCL2 and STAT3, previously associated with hypopharyngeal cancer, caused by acidic bile." (PMID 34850540, 2022). "We also showed that activation of p38 leads to downregulation of JNK and its downstream target STAT3, leading to decreased expression of Bcl-2, which in turn, results in inhibition of cell growth and induction of apoptosis and autophagy in metformin treated-hypopharyngeal cancer FaDu cells." (PMID 33652909, 2021).
hypothyroidism (7 papers, 2016 to 2025). Abnormally low levels of thyroid hormone. "Hypothyroidism caused overexpression of CHOP (163.3% and 300%), Casp12 (158% and 323%), and Bax (210% and 386%), while downexpression of Bcl2 levels was observed in both the PTU and PTU+IR groups, respectively (p<0.001)." (PMID 37368180, 2023). "Furthermore, our data provide candidate molecular mechanisms (deregulated expression of Bcl2, Zfp36l2, Egr1 and Hmga1) for the pesticides-induced hypothyroidism." (PMID 27905518, 2016).
ischemia reperfusion injury (7 papers, 2013 to 2024). Adverse functional, metabolic, or structural changes in ischemic tissues resulting from the restoration of blood flow to the tissue (reperfusion), including swelling; hemorrhage; necrosis; and damage from free radicals. "Overexpression of Bcl-2 has been linked to protection of cell apoptosis by inhibition of cytochrome c releases, while depletion of Bax protein has been shown to reduce cell death in ischemia reperfusion injury in mice." (PMID 23341883, 2013). "Bcl-2 is an anti-apoptotic protein localized in the outer membrane of the mitochondria; overexpression of Bcl-2 in neurons can inhibit neuron apoptosis induced by ischemia-reperfusion injury by maintaining the integrity of mitochondria." (PMID 30038574, 2018). "It has been shown that mdivi-1 inhibits apoptosis by upregulating the expression of anti-apoptotic protein Bcl-2 and downregulating pro-apoptotic protein Bax in primary hippocampal cells exposed to ischemia-reperfusion injury." (PMID 28891994, 2017). "TIIA has been demonstrated to decrease Bax/Bcl-2 ratio in a rat model of ischemia reperfusion injuries in vivo, and to regulate Bax/Bcl-2 ratio in neonatal cardiomyocytes treated with doxorubicin." (PMID 23341883, 2013). "At the same time, Senegenin in the treatment of postoperative and cognitive dysfunction, as well as ischemia-reperfusion injuries is associated with the regulation of JNK signaling pathway, the inhibition of NADPH oxidase and caspase-3 activity, the increase of Bcl-2/Bax." (PMID 35924058, 2022). "In animal model of ischemia-reperfusion injury, inhibitors of RhoA/ROCK signaling pathways demonstrate a cardioprotective effect, which is realized through the activation of MAPK and NFkB signaling pathways and a reduction in Bcl-2 levels, leading to a decrease in the apoptotic activity of cells." (PMID 33352947, 2020).
kidney injury (7 papers, 2019 to 2025). Trauma to the kidney. "We previously showed that meprin β modulates cellular survival (BCL-2) through IL-6/JAK/STAT signaling pathway in IR-induced kidney injury." (PMID 39975921, 2025). "We next analyzed apoptosis by examining Bcl-2 and Cleaved Caspase-3, which are hallmarks of apoptosis, to further clarify the role of apoptosis in cisplatin-induced kidney injury in vivo." (PMID 36193072, 2022). "We found that the pro-apoptotic protein Bad was upregulated, the anti-apoptotic protein Bcl-2 was downregulated, and caspase was activated in cisplatin-induced kidney injury." (PMID 35844954, 2022). "Taken together, these data suggest a crosstalk between apoptotic/anti-apoptotic Bcl-2 proteins and ceramide-producing enzymes in oxidant-induced kidney injury." (PMID 35409370, 2022). "Further studies are needed to determine the mechanism by which Bcl-2 proteins prevent ROS-induced ceramide formation in oxidant-induced kidney injury." (PMID 35409370, 2022). "Moreover, it was reported that an increased Bax/Bcl-2 ratio and the cleaved form of caspase-3, which are apoptotic markers, are reversed by paricalcitol treatment in gentamicin-induced kidney injury." (PMID 31527864, 2019).
laryngeal squamous cell carcinoma (7 papers, 2019 to 2025). A squamous cell carcinoma that arises from the larynx. "It is known that a high Bax/Bcl-2 ratio in laryngeal squamous cell carcinoma is related to favorable prognosis, decreased risk of patient relapse, and higher disease-free survival." (PMID 31861952, 2019). "The forced expression of hsa-miR-4497 suppresses proliferation and colony formation while inducing the apoptosis of laryngeal squamous cell carcinoma cells by repressing antiapoptotic Bcl-2 proteins." (PMID 35743310, 2022). "Epstein–Barr virus DNA positivity, age ≥ 55 years, cigarette smoking, and high BCL-2, B2M, and CD161 expression were identified as independent risk factors for primary laryngeal squamous cell carcinoma." (PMID 33917480, 2021). "Up-regulated Bcl-2 contributes to the development of laryngeal squamous cell carcinoma and inhibits cell apoptosis." (PMID 32792866, 2020).
leishmaniasis (7 papers, 2016 to 2025). Infectious disease that is transmitted through the bite of hematophagous female phlebotomine sand flies. "Our in silico approach involved predicting the affinities of MIL and NMIL to critical proteins involved in leishmaniasis, including Vascular Endothelial Growth Factor A (VEGF-A), the Kinase insert domain receptor (KDR1), and apoptotic-regulator proteins (Bcl-2-associate)." (PMID 38291076, 2024). "Targeting apoptotic pathways and the Bcl-2 ortholog in Leishmania may provide effective anti-leishmanial therapies, as shown by the successful use of miltefosine, an anticancer drug, known to induce apoptosis-like cell death in Leishmania sp., in treating leishmaniasis." (PMID 39946620, 2025).
lupus nephritis (7 papers, 2017 to 2025). Glomerulonephritis in the context of systemic lupus erythematosus. "Previous studies showed that TUG1 contributed to the protection of NF-κB inhibition after kidney injury in murine models of SLE, and TUG1 alleviated LPS-induced mesangial cell injury through regulation of the miR-153-3p/Bcl-2 axis in lupus nephritis." (PMID 37511572, 2023). "In contrast, HGC-TAC treatment did not affect the protein expression of the ratio of bax/bcl-2, cleaved caspase 3, and cytochrome compared to untreated lupus nephritis mice." (PMID 33865397, 2021).
myeloproliferative neoplasm (7 papers, 2011 to 2023). A clonal hematopoietic stem cell disorder, characterized by proliferation in the bone marrow of one or more of the myeloid (i.e., granulocytic, erythroid, megakaryocytic, and mast cell) lineages. "Navitoclax, a novel Bcl-2 inhibitor, exhibits cytotoxic activity in myeloproliferative neoplasm (MPN)-derived cell lines and in vitro specimens." (PMID 36701037, 2023). "Bcl-2 is a bona fide direct target of STAT5 so that STAT5 requires the N-domain for the suppression of miR15/16, induction of Bcl-2, and induction of survival signaling in mast cells and myeloproliferative neoplasms (MPNs)." (PMID 30510630, 2018). "For example, BCL2 gene (spans approximately 200 kbp), which is the first discovered anti-apoptotic gene, is located within FRA18B, whereas it is known that breakpoints and translocations within this region disrupt its function and lead to myeloproliferative diseases." (PMID 27625703, 2016).
pulmonary hypertension (7 papers, 2011 to 2021). Increased pressure within the pulmonary circulation due to lung or heart disorder. "As to the correlation between Notch-1 and endothelial cell apoptosis, a recent study has demonstrated that Notch-1 could inhibit endothelial cell apoptosis in pulmonary arterial hypertension via Bcl-2 and Survivin." (PMID 31343412, 2019). "Genes involved in cell proliferation, the cyclin family of genes and BCl2, were upregulated in the right ventricle of rats with pulmonary hypertension induced by monocrotaline, and the same was the case for cyclin D1 and D2 as well as BCl2 in the present study." (PMID 21246034, 2011). "However, other studies observed the upregulation of BCL-2 in pulmonary hypertension." (PMID 27304885, 2016). "(2015) during an investigation on pulmonary hypertensive mice demonstrated that treatment with salidroside reduces RVH in treated mice and raises Caspase-3, BAX, A2aR and reduces BCL2 expression in PASMCs." (PMID 32226378, 2020).